ENSG00000300902 (novel transcript)
Gene: Long non-coding RNA gene on chromosome 12 (97,471,782 to 97,568,746, reverse strand). Ensembl gene ENSG00000300902.
Gene Ontology:
Biological process: miRNA-mediated post-transcriptional gene silencing
Cellular component: RISC complex